ALDH2 (aldehyde dehydrogenase 2 family member)
Diseases named in the same sentence as ALDH2 in open-access papers (continued):
Sharing a sentence is not in itself a finding about the gene and the disease.
lymphopenia (1 paper, 2020). Reduction in the number of lymphocytes. "In summary, combined inactivation of the aldehyde-clearing enzymes ALDH2 and ADH5 leads to perinatal lethality, growth failure, lymphopenia, and lymphoid malignancies." (PMID 33147438, 2020).
metastatic melanoma (1 paper, 2025). A melanoma that has spread from its primary site to another anatomic site. "Knocking out ALDH2 in the A375 human metastatic melanoma cell line, which normally expresses ALDH2, enhances MAPK/ERK activation and promotes tumor growth." (PMID 40558540, 2025). "Examination of human metastatic melanoma cell lines confirmed that most had ALDH2 downregulation (ALDH2-low) compared to primary melanocytes." (PMID 40558540, 2025). "Similar to the CCLE dataset, two-thirds of human metastatic melanoma cell lines showed reduced ALDH2 expression levels compared to normal skin cells, while one-third displayed normal expression." (PMID 40558540, 2025). "In this study, we demonstrate that decreased ALDH2 gene expression in metastatic melanoma correlates with worse patient survival." (PMID 40558540, 2025). "To understand its clinical relevance, we examined the correlation between ALDH2 gene expression levels and overall survival in metastatic melanoma patients from TCGA with complete pathoclinical data." (PMID 40558540, 2025). "Analysis of TCGA dataset revealed that low ALDH2 expression correlates with poorer survival in metastatic melanoma." (PMID 40558540, 2025). "Next, we examined ALDH2 expression in human metastatic melanoma cell lines." (PMID 40558540, 2025).
metastatic tumors (1 paper, 2012). "The expression of ALDH2 and ALDH3A2 were significantly down-regulated in primary tumor samples and further down-regulated in metastatic tumors, similar to AOX1 expression." (PMID 23119026, 2012).
mortal (1 paper, 2020). "Interestingly, we also found that the frequency of AA in individuals ≥65 years old was lower than in other age groups, especially 18–29, with p = 0.01, which may imply that the ALDH2 rs671 mutation can induce other mortal diseases and aging independently of CVDs." (PMID 33276716, 2020).
mucinous ovarian cancer (1 paper, 2018). An invasive malignant neoplasm that arises from the ovary and is characterized by the presence of malignant epithelial cells that contain intracytoplasmic mucin and may resemble the epithelial cells of the endocervix or gastrointestinal tract. "In conclusion, we observed an inverse association between the Lys allele of rs671 in ALDH2 and mucinous ovarian cancer risk in an Asian population." (PMID 29247577, 2018). "Because the rs671 Lys allele causes ALDH2 inactivation leading to increased acetaldehyde exposure, the observed inverse genetic association with mucinous ovarian cancer is inferred to mean that alcohol intake may be a risk factor for this histotype." (PMID 29247577, 2018).
nicotine addiction (1 paper, 2014). "We investigated six variants known to influence nicotine addiction or alcohol metabolism, including rs16969968 (CHRNA5), rs578776 (CHRNA3), rs1229984 (ADH1B), rs698 (ADH1C), rs1573496 (ADH7), and rs4767364 (ALDH2)." (PMID 24505444, 2014).
obstructive lung disease (1 paper, 2017). "However, our results suggest that, in addition to the ALDH2 loss of function, the presence of several other genetic and environmental influences is required to inflect a clinically observable obstructive lung disease." (PMID 28431562, 2017).
orthostatic hypotension (1 paper, 2013). Sudden fall of the blood pressure of at least 20/10 mm Hg when a person stands up. "ALDH2*2 allele carriers exhibit a marked rise in the level of acetaldehyde in the blood and develop acute cardiovascular reactions, such as facial flushing, tachycardia and orthostatic hypotension, following alcohol consumption." (PMID 24028448, 2013).
osteoarthritis (1 paper, 2025). A noninflammatory degenerative joint disease occurring chiefly in older persons, characterized by degeneration of the articular cartilage, hypertrophy of bone at the margins and changes in the synovial membrane. "The DSCR1-1/CREB1/ALDH2/Wnt/β-catenin axis has been demonstrated to be involved in the etiology of osteoarthritis." (PMID 40968356, 2025). "ALDH2 activation subsequently blocks the Wnt/β-catenin signaling pathway, inhibiting chondrocyte apoptosis and improving osteoarthritis." (PMID 40968356, 2025). "ALDH2 is involved in slowing the progression of osteoarthritis by inhibiting oxidative stress, inflammation, and apoptosis through the regulation of aquaporin-4 expression." (PMID 40968356, 2025). "During the progression of osteoarthritis, down syndrome candidate region 1–1 (DSCR1-1) can inhibit chondrocyte apoptosis by regulating the cAMP-responsive element protein 1 (CREB1)/ALDH2/Wingless and int-1 (Wnt)/β-catenin axis." (PMID 40968356, 2025).
paroxysmal AF (1 paper, 2022). "The frequency of ALDH2*2 was similar between the paroxysmal AF group and persistent AF group in all (21.4% vs. 26.3%, P = 0.237) and male patients (21.6% vs. 20.2%, P = 0.774)." (PMID 36426220, 2022). "In female patients with AF, the frequency of ALDH2*2 was 38.5% in the persistent AF group, whereas it was 21.2% in the paroxysmal AF group (P = 0.016)." (PMID 36426220, 2022).
periodontal disease (1 paper, 2021). "The results from this study may provide important clinical information and a potential therapeutic target for the treatment or prevention of dental bone loss in periodontal disease, especially for the large population of East Asians carrying the vulnerable ALDH2*2 genotype." (PMID 33925003, 2021).
pharyngeal squamous cell carcinoma (1 paper, 2016). A squamous cell carcinoma that arises from the pharynx. "We investigated the characteristics of ESCC, and the relationship between metachronous esophageal and/or pharyngeal squamous cell carcinoma (SCC) and the ADH1B & ALDH2 risk alleles." (PMID 27038040, 2016).
prostatic disease (1 paper, 2025). "Additional contributors to prostatic disease progression include ALDH2 and CDS1, which are implicated in glycerophospholipid-related pathways." (PMID 40626307, 2025).
retinal diseases (1 paper, 2020). "Together, the reduced level of ALDH2 in animal models of RP and DR implies that ALDH2 might play a universal role in the pathogenesis of retinal diseases." (PMID 32070320, 2020). "In terms of the reported ALDH2-induced protection against aldehyde-related diseases, we speculated that ALDH2 might also be able to alleviate retinal diseases." (PMID 32070320, 2020).
Right ventricular hypertrophy (1 paper, 2022). In this case the right ventricle is more muscular than normal, causing a characteristic boot-shaped (coeur-en-sabot) appearance as seen on anterior- posterior chest x-rays. "In this study, we demonstrated that ALDH2 deficiency exacerbates pulmonary artery muscularization, right ventricular hypertrophy, fibrosis, and right-sided heart failure by regulating autophagy." (PMID 35770049, 2022).
schizophrenia (1 paper, 2013). A major psychotic disorder characterized by abnormalities in the perception or expression of reality. "Proteomic profiling of human anterior cingulate cortex from patients with schizophrenia has shown differential expression of ALDH2." (PMID 23521751, 2013).
Shock (1 paper, 2021). The state in which profound and widespread reduction of effective tissue perfusion leads first to reversible, and then if prolonged, to irreversible cellular injury. "Inhibition of oxidative stress responses in hemorrhagic shock of alveolar damage and of immune cell infiltration were also observed through increased ALDH2 activity via AldA_1 in animal models." (PMID 34436489, 2021).
stress-related disorder (1 paper, 2023). Stress-related disorders are mental health disorders that are a result of an atypical response to both short and long-term anxiety due to physical, mental, or emotional stress. "ALDH2 levels have been implicated in stress-related disorders 25,26, which can affect the comorbidity profile of cancer patients." (PMID 37476181, 2023).
synucleinopathies (1 paper, 2024). "Sleep deprivation can exacerbate synucleinopathies, increase cerebrospinal fluid levels of amyloid-beta 42 and tau peptides, and decrease ALDH2 enzyme activity, leading to neurotoxic aldehyde accumulation and neuronal degeneration." (PMID 39449309, 2024).
triple-negative breast carcinoma (1 paper, 2023). An invasive breast carcinoma which is negative for expression of estrogen receptor (ER), progesterone receptor (PR), and human epidermal growth factor receptor 2 (HER2). "We also found a statistically significant SNP*alcohol consumption interaction between triple negative breast cancer and rs3858704-A in the ALDH2 locus on chromosome 12 [ORint (95% CI) = 6.28 (2.50,15.73), pint = 8.97 × 10–5]." (PMID 37308906, 2023). "In addition, there was a statistically significant interaction of rs3858704-A in ALDH2 with consumption of ≥ 7 drinks/week on odds of triple negative breast cancer (≥ 7drinks per week OR = 4.41, < 7 drinks per week OR = 0.57, pint = 8.97 × 10–5)." (PMID 37308906, 2023).
Ureteral obstruction (1 paper, 2024). Obstruction of the flow of urine through the ureter. "In mouse models of unilateral ureteral obstruction and folic acid nephropathy, reduced ALDH2 levels and elevated acrolein were observed in kidneys, especially in ALDH2 Glu504Lys–knockin mice." (PMID 39226171, 2024). "To substantiate our clinical observation regarding the reduction of ALDH2 and acrolein accumulation in kidney disease progression, we utilized 2 kidney fibrosis models, the unilateral ureteral obstruction (UUO) model and folic acid nephropathy (FAN), in wild-type mice." (PMID 39226171, 2024).
Uterine leiomyoma (1 paper, 2017). The presence of a leiomyoma of the uterus. "In uterine leiomyomas, HMGA2 fusion transcripts were reported with various sequences including COX6C (8q22.2), ALDH2 (12q24.12), CCNB1IP1 (14q11.2), RAD51B (14q24.1), and RTVL-H 3_ LTR (21q21.2)." (PMID 28591699, 2017).
Ventriculomegaly (1 paper, 2019). An increase in size of the ventricular system of the brain. "Further, the activity of ALDH2 was about fivefold lower in the blood of AD patients than age-matched healthy controls, and magnetic resonance imaging (MRI) revealed marked atrophy in the left prefrontal lobe and significant ventriculomegaly (marked white triangle) compared to healthy controls." (PMID 31815201, 2019).
cancer (194 papers, 2002 to 2026). A tumor composed of atypical neoplastic, often pleomorphic cells that invade other tissues. "ALDH2 was found to be associated with cancer stemness and metastasis in CRC through activating β-catenin signaling." (PMID 41550766, 2026). "The ALDH2*2 mutation has further been linked to increased risk of long-term systemic diseases, such as cancer and Alzheimer’s disease, with the influence of these risks modulated by alcohol intake." (PMID 40564981, 2025). "Among these, the functional SNPs of ALDH2 (rs671) have been associated with the development of cancers of the upper aerodigestive tract, head, and neck." (PMID 40563518, 2025). "A recent study on ALDH2 polymorphisms and the attributable burden of cancer in East Asia revealed that the estimated burden of alcohol-related cancer increased when ALDH2 polymorphisms were considered." (PMID 40563518, 2025). "The rationale for focusing on personalized prediction of EC is underscored by the high prevalence of the ALDH2*2 allele among East Asians, which can lead to a dramatic increase in cancer risk among heavy drinkers." (PMID 40156023, 2025). "In conclusion, ROS induced by ALDH2 deficiency can be tolerated in cancer cells, resulting in tumor progression; whereas ROS is intolerant in normal cells, resulting in the elimination of BASCs." (PMID 38292172, 2024). "Paclitaxel-treated cancer cells show stronger expression of stem-associated ALDH2, SOX2, and Nanog markers than untreated cells." (PMID 39062149, 2024). "People with the ALDH2*2 variant allele are known to be more susceptible to alcohol- or age-related neuronal damage or cancer compared to their unaffected counterparts." (PMID 38891060, 2024). "Carrying this ALDH2*2 genetic variant has important health implications with respect cancer risk which is increased when carriers of the ALDH2*2 genetic variant frequently use of alcohol or tobacco products." (PMID 38895023, 2024). "The potential mechanisms of the association of low ALDH2 with cancer aggressiveness include the possible interaction with another member of the ALDH family, ALDH6A1, based on the gene and protein co-expression network analysis." (PMID 37476181, 2023). "ALDH2 polymorphisms (Glu504Lys) is also correlated with occurrence and progression of cancer but the role is only partially understood." (PMID 37173331, 2023). "Our findings provide strong evidence of additive and synergic risks of ADH1B and ALDH2 variants for alcohol‐related disorders and cancer." (PMID 35670037, 2023). "Here, we performed a large‐scale hospital‐based case–control study to explore the associations of ADH1B and ALDH2 variants with the risks of alcohol‐related disorder and cancer." (PMID 35670037, 2023). "Previous research has linked ALDH2 dysfunction and suppression to a variety of human diseases and cancers." (PMID 36936815, 2023). "There were interactions between ALDH2-rs671 genotype and self-reported alcohol intake for alcohol-related cancers, other cancers, and all-cause mortality, with higher risks among male drinkers with AG compared with GG genotypes (appendix p29)." (PMID 38000378, 2023). "This essentially excluded the possibility that ALDH2 deficiency drastically abrogates or accelerates the cancer development in HBOC patients." (PMID 36345163, 2023). "The aim of the research was to evaluate the associations of ADH1B rs1229984 and ALDH2 rs671 with the risks of alcohol‐related disorder and cancer." (PMID 35670037, 2023). "Carrying the dysfunctional ALDH2*2 variant not only increases the risk of multiple tumors among UADT cancer patients, but also leads to a poorer prognosis of these patients." (PMID 35330099, 2022). "Asian drinkers have a higher risk of developing cancer because of mutations in ALDH2 and ALDH2 deficiency exacerbates alcohol-associated HCC development both in patients and in mouse models." (PMID 34928471, 2022).
cancer (continued). "Those with a mutated ALDH2–2 allele accumulated acetaldehyde had a higher risk of alcohol-related cancers than those with a wild-type allele after alcohol ingestion." (PMID 35565397, 2022). "The role of ALDH2 deficiency in cancer progression, metastasis, prognosis and clinical treatment outcome in other cancer that not directly related to alcohol can also be the focus of future research." (PMID 35330099, 2022). "A genetic variant of aldehyde dehydrogenase 2 (ALDH2 rs671, Glu504Lys) can also contribute to cancer development in alcohol drinkers." (PMID 35565397, 2022). "This large-scale genetic study utilizing the China Kadoorie Biobank (CKB) data provided the strongest direct causal relationship and interaction between alcohol use, cancer and ALDH2 genotype." (PMID 35749303, 2022). "Among men, those with ALDH2‐rs671 AA genotype had 14% lower risk of any cancer (HR = 0.86 [95% CI: 0.73‐1.00]) and 31% (0.69 [0.53‐0.90]) lower risk of IARC alcohol‐related cancers than those with GG genotype." (PMID 35048370, 2022). "Typically, these meta-analyses focused on single disease outcome such as hypertension, cardiovascular disease, or cancer, and showed both deleterious and protective associations of ALDH2 rs671 polymorphism with these diseases." (PMID 36050775, 2022). "The ALDH2 gene rs671 polymorphism was associated with the overall cancer risk in the Asian population." (PMID 34850600, 2022). "The spectrum of different diseases associated with ALDH2 deficiency and aldehyde toxicity is well covered by many recent reviews, and includes a higher risk of cancer and cardiovascular disease." (PMID 35749303, 2022). "The function of the inactive ALDH2*2 missense mutation and its interplay with its transcriptional level and post-translational regulation in different types of cancer progression and prognosis remains to be determined." (PMID 35330099, 2022). "The East Asian-specific dysfunctional ALDH2*2 missense mutation is a genetic risk factor for UADT cancer." (PMID 35330099, 2022). "ALDH2*2 carriers also correlated with a greater risk of having metachronous cancer in ESCC patients." (PMID 35330099, 2022). "Previous studies have reported interactions between ALDH2‐rs671 and alcohol consumption on upper aerodigestive cancer risk in East Asian populations." (PMID 35048370, 2022). "By analyzing peripheral blood leukocytes between PDAC individuals and non-cancer controls, researchers uncovered that the ALDH2 gene mutants showed a strong association with PDAC." (PMID 36499358, 2022). "In summary, both ALDH2 and its associated metabolites are more or less directly or potentially related to cancer." (PMID 35517510, 2022). "In that paper, the authors have collected many interesting clinical and translational studies on ALDH2 variant and cancer therapy." (PMID 34940794, 2022). "Many studies have demonstrated that the genetic effect of ADH1B and ALDH2 increase the risk of different types of cancers." (PMID 34680942, 2021). "Current or former flushing has been shown to be a predictor of the risk of cancer as a surrogate marker of inactive ALDH2 in various drinking populations." (PMID 34310648, 2021). "Low expression or genetic polymorphism of ALDH2 dramatically reduce its enzyme activity, and the accumulation of acetaldehyde can further damage normal cells and lead to cancers." (PMID 35096916, 2021). "Further investigations of other cancer types, and using the ALDH2‐rs671 gene variant, are warranted." (PMID 33634874, 2021). "Among the top 50 DEGs, the cancer stem cell marker aldehyde dehydrogenase 2 (ALDH2), associated with drug efflux/resistance, was down-regulated after BCAR1 knockdown." (PMID 34830244, 2021). "The increase and reduction of membranous PD‐L1 protein expression on cancer cells was caused by forced overexpression and knockdown of ALDH2, respectively." (PMID 34026438, 2021).